TRAJ3 (T cell receptor alpha joining 3)
Description:
J region of the variable domain of T cell receptor (TR) alpha chain that participates in the antigen recognition. Alpha-beta T cell receptors are antigen specific receptors which are essential to the immune response and are present on the cell surface of T lymphocytes. Recognize peptide-major histocompatibility (MH) (pMH) complexes that are displayed by antigen presenting cells (APC), a prerequisite for efficient T cell adaptive immunity against pathogens. Binding of alpha-beta TR to pMH complex initiates TR-CD3 clustering on the cell surface and intracellular activation of LCK that phosphorylates the ITAM motifs of CD3G, CD3D, CD3E and CD247 enabling the recruitment of ZAP70. In turn ZAP70 phosphorylates LAT, which recruits numerous signaling molecules to form the LAT signalosome. The LAT signalosome propagates signal branching to three major signaling pathways, the calcium, the mitogen-activated protein kinase (MAPK) kinase and the nuclear factor NF-kappa-B (NF-kB) pathways, leading to the mobilization of transcription factors that are critical for gene expression and essential for T cell growth and differentiation. The T cell repertoire is generated in the thymus, by V-(D)-J rearrangement. This repertoire is then shaped by intrathymic selection events to generate a peripheral T cell pool of self-MH restricted, non-autoaggressive T cells. Post-thymic interaction of alpha-beta TR with the pMH complexes shapes TR structural and functional avidity.
Gene: T-cell receptor joining (J) gene on chromosome 14 (22,543,179 to 22,543,240, forward strand). Ensembl gene ENSG00000211886.
Subcellular location: Cell membrane
Gene Ontology:
Cellular component: plasma membrane